SAMD11 (sterile alpha motif domain containing 11)
Description:
Component of a Polycomb group (PcG) multiprotein PRC1-like complex, essential for establishing rod photoreceptor cell identity and function by silencing nonrod gene expression in developing rod photoreceptor cells.
Synonyms: MGC45873; MRS
Tractability: PROTAC: UniProt records ubiquitination sites on it; ubiquitination databases record sites on it.
Gene: Protein-coding gene on chromosome 1 (923,923 to 944,575, forward strand). Ensembl gene ENSG00000187634.
Subcellular location: Nucleus
Subcellular location (Human Protein Atlas): Nucleoplasm; Vesicles
Gene Ontology:
Molecular function: protein binding; chromatin binding; DNA-binding transcription repressor activity, RNA polymerase II-specific; histone binding
Biological process: negative regulation of DNA-templated transcription; retinal rod cell development; negative regulation of transcription by RNA polymerase II
Cellular component: nucleus; PRC1 complex
Genetic constraint (gnomAD): Loss-of-function variants: 73 observed, 50.14 expected, observed/expected ratio (o/e) 1.46, 90% interval 1.2 to 1.76. The synonymous counts are far from expectation, so gnomAD's model fits this gene poorly and the ratio says little. Missense variants: 1,301 observed, 816.84 expected, observed/expected ratio (o/e) 1.59, 90% interval 1.52 to 1.67. Synonymous variants: 605 observed, 362.26 expected, observed/expected ratio (o/e) 1.67, 90% interval 1.56 to 1.79.
Homologues: Orthologues: macaque SAMD11 (96% identical), dog SAMD11 (88% identical), pig SAMD11 (82% identical), guinea pig SAMD11 (82% identical), rat Samd11 (78% identical), chimpanzee SAMD11 (77% identical), zebrafish samd11 (54% identical), tropical clawed frog samd11 (47% identical), mouse Samd11 (46% identical), Drosophila melanogaster l(3)mbt (10% identical), Drosophila melanogaster Sfmbt (7% identical), Caenorhabditis elegans mbtr-1 (5% identical), and 1 more. Paralogues in human: SAMD7 (13% identical), PHC2 (13% identical), PHC3 (12% identical), PHC1 (12% identical), L3MBTL1 (12% identical), L3MBTL3 (11% identical), L3MBTL4 (10% identical), SFMBT1 (9% identical), SCMH1 (8% identical), SCML2 (8% identical), SFMBT2 (8% identical), MBTD1 (7% identical), and 6 more.
Diseases named in the same sentence as SAMD11 in open-access papers:
SAMD11 is named in the same sentence as 17 diseases in open-access papers, as found by Europe PMC text mining. Sharing a sentence is not in itself a finding about the gene and the disease. The quoted sentences say what the papers report.
autism (2 papers, 2016 to 2022). Persistent deficits in social interaction and communication and interaction as well as a markedly restricted repertoire of activity and interest as well as repetitive patterns of behavior. "The top down-regulated gene was a transcriptional co-repressor involved in photoreceptor degradation and possibly autism (Sterile Alpha Motif Domain Containing 11, SAMD11, PFDR ≤ 8.3 × 10−5, mean logFC = − 1.936)." (PMID 36271102, 2022).
Intellectual disability (1 paper, 2016). "However, none of patients carrying the novel mutations and variants in SAMD11 here reported suffer from autistic behaviour, related-neurodevelopmental disorders or intellectual disability." (PMID 27734943, 2016).
melanoma (1 paper, 2021). A malignant, usually aggressive tumor composed of atypical, neoplastic melanocytes. "Apart from that, such mutation patterns have been identified in melanoma associated genes, like OR4F5 and SAMD11, validating the specific role of such mutational patterns in melanoma." (PMID 34513841, 2021).
night blindness (1 paper, 2016). Inability to see clearly in dim light. "Supporting this last supposition, the patients carrying the deleterious nonsense mutation in SAMD11 developed a late rod affectation with first symptoms of night blindness and field constriction in the third to fourth decade of life." (PMID 27734943, 2016).
oesophageal cancer (1 paper, 2021). "Moreover, overexpression of SAMD11 is associated with radioresistance in oesophageal cancer cells." (PMID 34885166, 2021).
osteosarcoma (1 paper, 2022). A usually aggressive malignant bone-forming mesenchymal neoplasm, predominantly affecting adolescents and young adults. "In order to determine which lncRNA was involved in osteosarcoma, lncRNAs including lnc-SELPLG-2:1, lnc-DDX47–3:1, lnc-ZNF77–165:3, lnc-SRSF2–9:2, lnc-SAMD11–1:1, and lnc-PPP1R9B-4:2 were detected by RT-qPCR to determine if their sequences were consistent with sequencing results." (PMID 36199080, 2022).
ovarian carcinoma (1 paper, 2022). A malignant neoplasm originating from the surface ovarian epithelium. "Furthermore, correlation analysis between 182 DEGs and MEX3A was applied using TCGA ovarian cancer data to obtain 7 DEGs (CSNKE1, OBSL1, DNASE1, ZNF711, TIMELESS, SAMD11, and BCL9) that were positively associated with MEX3A expression (Spearman’s correlation≥0.3)." (PMID 35715407, 2022).
retinal dystrophies (1 paper, 2016). "Identification of SAMD11 as causative gene in two RP families highlights a putatively important role for other SAM-related proteins, such SAMD7, in the pathogenesis of the retinal dystrophies." (PMID 27734943, 2016).
retinitis pigmentosa (1 paper, 2016). Retinitis pigmentosa (RP) is an inherited retinal dystrophy leading to progressive loss of the photoreceptors and retinal pigment epithelium and resulting in blindness usually after several decades. "Further research on SAMD11 is expected to provide insights into its specific role in the retina and its pathogenic mechanism responsible for Retinitis Pigmentosa." (PMID 27734943, 2016).
thyroid cancer (1 paper, 2025). "The same study identified SAMD11 as a target gene of METTL16, with METTL16 regulating SAMD11 expression through m6A modification, thus playing a crucial role in thyroid cancer." (PMID 40819127, 2025).
tumor (2 papers, 2017 to 2024). "Unfortunately, there is no literature documenting that SAMD11 is related to the tumor immune microenvironment." (PMID 39072320, 2024).
SAMD11 also shares sentences with these, for which no sentence is quoted: breast carcinoma (2 papers); autism spectrum disorder (1); autosomal recessive retinitis pigmentosa (1); Bardet-Biedl syndrome (1); neurodevelopmental disorder (1); retinal degeneration (1).